MRPL16 (mitochondrial ribosomal protein L16)
Synonyms: L16mt; MRP-L16; PNAS-111; FLJ20484; uL16m
Tractability: Small molecule: a structure with a bound ligand is known. PROTAC: ubiquitination databases record sites on it; its protein half-life has been measured.
Gene: Protein-coding gene on chromosome 11 (59,806,140 to 59,810,779, reverse strand). Ensembl gene ENSG00000166902.
Subcellular location: Mitochondrion
Pathways (Reactome):
Metabolism of proteins: Mitochondrial ribosome-associated quality control; Mitochondrial translation elongation; Mitochondrial translation initiation; Mitochondrial translation termination
Gene Ontology:
Molecular function: rRNA binding; structural constituent of ribosome
Biological process: mitochondrial translation; translation
Cellular component: mitochondrial large ribosomal subunit; mitochondrion; mitochondrial inner membrane; large ribosomal subunit; ribosome
Genetic constraint (gnomAD): Loss-of-function variants: 17 observed, 23.07 expected, observed/expected ratio (o/e) 0.74, 90% interval 0.5 to 1.11. The upper end of that interval is the gene's LOEUF score, 1.11, which puts it in group 4 of 6, group 1 being the genes least tolerant of losing a copy. Missense variants: 316 observed, 347.46 expected, observed/expected ratio (o/e) 0.91, 90% interval 0.83 to 1. Synonymous variants: 103 observed, 119.93 expected, observed/expected ratio (o/e) 0.86, 90% interval 0.73 to 1.01.
Homologues: Orthologues: chimpanzee MRPL16 (99% identical), macaque MRPL16 (97% identical), pig MRPL16 (90% identical), rabbit MRPL16 (86% identical), guinea pig MRPL16 (85% identical), mouse Mrpl16 (84% identical), rat Mrpl16 (84% identical), zebrafish mrpl16 (57% identical), tropical clawed frog mrpl16 (55% identical), Drosophila melanogaster mRpL16 (45% identical), Caenorhabditis elegans mrpl-16 (30% identical).
Diseases named in the same sentence as MRPL16 in open-access papers:
MRPL16 is named in the same sentence as 2 diseases in open-access papers, as found by Europe PMC text mining. Sharing a sentence is not in itself a finding about the gene and the disease. The quoted sentences say what the papers report.
breast carcinoma (1 paper, 2023). "As for MRPL16, few studies have reported its functions to date and only one study reported that low levels of MRPL16 significantly indicated poor prognosis in breast cancer patients." (PMID 37274336, 2023).
colorectal tumors (1 paper, 2021). "bL21m (MRPL21) and uL16m (MRPL16) have been identified as a potential prognostic marker in colorectal tumors." (PMID 34071057, 2021).